EGFR (epidermal growth factor receptor)
Diseases named in the same sentence as EGFR in open-access papers (continued):
Sharing a sentence is not in itself a finding about the gene and the disease.
cancer (continued). "Consequently, both EGFR and EGFRvIII are being targeted for cancer therapy." (PMID 21388543, 2011). "Thus, Ack1 has emerged as a candidate for anti cancer drug design; Ack1 inhibitors could potentially be used in combination therapies with inhibitors of other tyrosine kinases, such as EGFR." (PMID 21637378, 2011). "Thus, we determined whether β-catenin-mediated promotion of transcription in cancer cells also depended on EGFR activity." (PMID 20302655, 2010). "Therefore EGFR is a well-recognized anti-cancer therapeutic target." (PMID 20074357, 2010). "EGFR activation/alteration may contribute to and sustain the high prevalence of this cancer." (PMID 20498858, 2010). "Moreover, carcinogenetic events which affect to EGFR may be behind the increased glucose uptake and survival of cancer cells through the stabilization of SGLT1 carrier, as it has been recently demonstrated." (PMID 20706540, 2010). "Additionally, it is possible that gene increase is associated with mutational activation of EGFR, serving as a surrogate marker for mutation, and would suggest that screening by FISH might be limited to cancers in which EGFR is frequently mutated." (PMID 20037743, 2010). "EGFR expression extent and intensity scores revealed by most of the study cases suggest that EGFR expressing carcinomas display pathological features of more aggression which may be attributable to the activation of different signaling pathways that control diverse biological processes." (PMID 20579333, 2010). "The combined activity of bortezomib and cetuximab in EGFR-positive solid cancers is unknown, though it is reasonable to postulate that this combination could be synergistic, given the preclinical observations that bortezomib upregulates EGFR expression in cancer cells." (PMID 19401697, 2009). "The immunobead RT-PCR method, developed here for detecting CTCs expressing EGFR, may provide an important future clinical application for monitoring the efficacy of systemic therapies through the real-time monitoring of EGFR-positive CTCs in cancer patients during their treatment." (PMID 19961621, 2009). "Thus, EGFR TKI may represent a novel therapeutic strategy which can attenuate TS expression in cancer cells." (PMID 19529774, 2009). "Furthermore, inappropriate activation of mammalian EGFR can lead to various forms of human cancers." (PMID 18197257, 2008). "Therefore, dual inhibition therapy designed to target EGFR and HER2 together may prove to be an ideal regimen for EGFR- or HER2-positive cancer patients." (PMID 19061514, 2008). "In the present study we sought to investigate whether negative targeting of TNK2 by siRNA could be used to inhibit cancer cell invasion, to establish the contribution of its effect on the EGFR and to consequently attempt to resolve the issue of TNK2's mechanism of action." (PMID 18435854, 2008). "In addition, mTOR targeting by the specific inhibitor everolimus not only results in significant antiproliferative activity but also restores sensitivity to anti-EGFR drugs in resistant cancer cells, producing a strong reduction of Akt activation, when used in combination with anti-EGFR drugs." (PMID 18319715, 2008). "Finally, considering the effect on adhesion and chemotactic cell migration and proliferation, these results suggest that targeting both EGFR and uPAR might provide an alternative method on cancer control by inhibiting both its growth and metastasis." (PMID 18519000, 2008). "Furthermore, our previous in vitro studies reported that the sequential administration of EGFR inhibitors after chemotherapy may enhance/maintain chemotherapy-induced cancer cell damage." (PMID 17173694, 2006). "Reintroduction of PTEN or pharmacological downregulation of the constitutive PI3K–Akt-pathway activity may be an attractive therapeutic strategy in cancers without the EGFR gene mutation." (PMID 15870831, 2005).
cancer (continued). "Thus, tamoxifen in the prevention setting may select for the outgrowth of EGFR or Her2 activated cancer cells that ultimately become ER- cancers." (PMID 16457695, 2005). "ZD1839 (‘Iressa’) is an orally active, selective epidermal growth factor receptor tyrosine kinase inhibitor (EGFR-TKI) that blocks signal transduction pathways implicated in the proliferation and survival of cancer cells and other host-dependent processes promoting cancer growth." (PMID 12888834, 2003). "ZD1839 (‘Iressa’) is an orally active, selective epidermal growth factor receptor–tyrosine kinase inhibitor (EGFR–TKI), which blocks signal transduction pathways implicated in proliferation and survival of cancer cells, and other host-dependent processes promoting cancer growth." (PMID 11986789, 2002). "ZD1839 (‘Iressa’) is an orally active, selective EGFR-TKI (epidermal growth factor receptor-tyrosine kinase inhibitor) that blocks signal transduction pathways implicated in the proliferation and survival of cancer cells, and other host-dependent processes promoting cancer growth." (PMID 11953865, 2002). "EGFR signalling is known to stimulate this pathway and it is likely that AT1R mediated EGFR-transactivation promotes the proliferative effects of AT1R in cancer." (PMID 41408463, 2026). "For example, two antibodies, cetuximab 137 and panitumumab 138, have been explored preclinically, both targeting the epidermal growth factor receptor (EGFR), also known as HER1, which is found to be overexpressed in several cancers." (PMID 41510167, 2026). "Genetic aberrations (e.g. EGFR and MYC amplifications) in cancer cells also lead to dysregulated transcriptional programs which render cancer cells highly dependent upon exceptionally high rates of transcription of genes critical to promoting proliferation." (PMID 41505030, 2026). "We demonstrate the flexibilityof this platform by equipping SpyTag-AAVswith DARPins targeting EGFR, EpCAM, and HER2, which successfully redirectedthe vector to the corresponding cancer cell lines." (PMID 41430475, 2026). "Together, these data suggest ZNRF3 and RNF43 as novel E3 ubiquitin ligases of EGFR and establish the inactivation of ZNRF3/RNF43 as a driver of increased EGFR signaling, ultimately promoting cancer progression." (PMID 41960900, 2026). "We demonstrated this modularity by equipping the vector withdifferent SpyCatcher-DARPin fusion proteins specific for EGFR, EpCAM,and HER2/ErbB2, thereby achieving efficient and specific transductionof corresponding cancer cell lines." (PMID 41430475, 2026). "Upon activation by ligands such as EGF, EGFR phosphorylates downstream effectors like STAT3, a transcription factor critical for cancer cell proliferation and survival." (PMID 41511366, 2026). "Network analysis highlighted STAT3, EGFR, SRC, IL-6, and AKT1 as key hub targets, with enrichment in cancer-related, EGFR resistance, and PI3K-Akt pathways." (PMID 42123459, 2026). "EGFR signaling, which requires ligand shedding by ADAM proteases, drives the progression of a variety of cancers, including breast, ovarian and lung." (PMID 41977126, 2026). "Functionally, oncogenic BRAF drives persistent activation of the MAPK/ERK pathway, which attenuates upstream EGFR/RAS signaling and thereby perturbs antitumor immune surveillance at multiple stages of the cancer-immunity mechanisms." (PMID 41596586, 2026). "Erlotinib, an epidermal growth factor receptor tyrosine kinase inhibitor (EGFR-TKI), is widely used in cancer therapy; however, hepatotoxicity limits its clinical use." (PMID 42123402, 2026). "Our results revealed that EGFR and HER2 FolTAC-dual v1.0 and Trastuzumab specifically inhibit SKBR3-WT cancer cells while sparing HFF-1 cells." (PMID 41038820, 2025). "Predicted targets of the five downregulated miRNAs were enriched for multiple cancer-related pathways, including PI3K–Akt, ErbB, EGFR inhibitor resistance, chemical carcinogenesis, and the “microRNAs in cancer” pathway." (PMID 41462933, 2025).
cancer (continued). "Costs of oral drugs including anti-cancer drugs such as ALK- and EGFR-targeted drugs and oral CT drugs, immunosuppressants, and non-cancer-related drugs were calculated using the prescription data." (PMID 41139898, 2025). "Several studies have demonstrated a strong link between the EGFR and CD73 signaling pathways in various cancers." (PMID 40191718, 2025). "targeted EGFR overexpression and Cetuximab (CTX) resistant cancer cells with cetuximab when utilized with camptothecin‐loaded polymer NPs." (PMID 40840553, 2025). "Epidermal Growth Factor Receptor (EGFR) proteins play several roles in cancer progression, including the promotion of cancer cell growth and resistance to chemotherapy." (PMID 40141140, 2025). "Beyond EGFR, SPINK proteins modulate metalloprotease activity, which contributes to extracellular matrix remodelling and facilitates cancer cell migration." (PMID 40872585, 2025). "Specific to individual cancer types, LUAD and LUSC have relatively high Hub-EGFR.Sig scores among cancers, and ample evidence has confirmed that EGFR tyrosine kinase inhibitors indeed prolong the PFS of NSCLC patients." (PMID 40574864, 2025). "Activation of EGFR subsequently initiates downstream signaling cascades involving PI3K/AKT and MAPK pathways that often are overexpressed in cancers." (PMID 40115248, 2025). "This research highlights the wider potential of RL in enhancing therapeutic decision-making for advanced EGFR-mutant NSCLC and other cancers." (PMID 39858018, 2025). "Under basal conditions, this microRNA targets EGFR, restraining EGFR/ERK signaling and inhibiting cancer-cell EMT, migration, and invasion." (PMID 41514658, 2025). "These substances target a variety of glycolytic components and offer promising treatment options for EGFR-TKI resistance and cancer cell growth inhibition." (PMID 40728967, 2025). "The dimerization of EGFR was demonstrated to require palmitoylation, induced by tyrosine kinase inhibitors (i.e., AEE788, gefitinib, and erlotinib) in a series of cancer cell lines including A549, MDA-MB-231, PC3, and DU145." (PMID 40004137, 2025). "Several investigations indicate that EGFR and HER-2 experience coamplification in numerous cancer types, including those of the breast, ovaries, prostate, colon, and other tissues." (PMID 41036428, 2025). "Using dual targeting of EGFR and HER2 as a representative application, we demonstrate its potential to counteract Traz/Lap resistance in HER2+ cancer models." (PMID 41038820, 2025). "Primary and acquired resistance to EGFR inhibition have been directly linked to overexpression of MET, and it is well established that EGFR and MET share similar pathway trajectories and phenotypical outcomes in cancer." (PMID 41115375, 2025). "PYCR1 interacts with EGFR, activating the PI3K–AKT pathway to enhance aerobic glycolysis and support cancer cell proliferation in bladder cancer." (PMID 41254241, 2025). "All three lymphocyte cell types showed enrichment in pathways strongly involved in immune cell response to cancer, like PD-L1/PD-1 checkpoint, ErbB, MAPK, TNF, PI3K/Akt/mTOR, EGFR, VEGF, NF-kappa B signaling." (PMID 40954493, 2025). "Contrary to the immune contexture of EGFR and ALK altered tumors, the KRAS driven NSCLC displays predominantly IE and inflamed TME types, which suggests a different route to cancer immune evasion." (PMID 40809430, 2025). "Our RNA expression and western blot analysis of the co-expression profile revealed that the EGFR and HER2 pairs are present in some of the cancer cell lines, with PD-L1 and VISTA demonstrating a broad spectrum across various cell lines." (PMID 41038820, 2025).
cancer (continued). "PFKFB3 is necessary for cancer cell migration and can be activated downstream of the EGF receptor (EGFR) by extracellular signal-regulated kinase (ERK), AMP-activated kinase (AMPK) or protein kinase A (PKA) signaling." (PMID 41159217, 2025). "A quantum-dot (QD)-incorporated micelle functionalized with an anti-epidermal growth factor receptor (EGFR) nanobody (Nb) and loaded with an anticancer drug, aminoflavone (AF), has been designed for targeted theranostic of EGFR-overexpressing cancers." (PMID 41304734, 2025). "EGFR is considered a key clinical target for therapeutic intervention in TNBC and many other cancers." (PMID 39942711, 2025). "Exosomes released from cancer cells contain TGF-β, PD-L1, and epidermal growth factor receptor (EGFR)." (PMID 39561105, 2025). "Overexpression of EGFR, which belongs to the ERBB family of RTKs, has been observed in different types of cancers, including breast." (PMID 40864816, 2025). "This narrative review aims to review key nutritional strategies in supporting targeted cancer therapies with a sequential focus on immune checkpoint inhibitor, PI3K inhibitor and EGFR-TKI treatments." (PMID 41425618, 2025). "The binding of OTA to EGFR can activate downstream signaling pathways, such as the PI3K-Akt signaling pathway, thereby promoting the survival and proliferation of cancer cells." (PMID 40864064, 2025). "EGFR is expressed in 25–75% of CRC cases, and its ligands, EGF and TGF-α, are found at higher levels in the mucosa surrounding malignant tumors than in the normal mucosa." (PMID 39852970, 2025). "Molecular docking and molecular dynamics simulations provided mechanistic insights into the binding interactions of these derivatives with key cancer-related targets, including Topoisomerase II, VEGFR2, c-Met, EGFR, and Estrogen Receptor Alpha (ERα)." (PMID 40610494, 2025). "Then, the correlation between Hub-EGFR.Sig and microsatellite instability (MSI) was analysed in pan-cancer samples." (PMID 40574864, 2025). "Consequently, cancer therapy is constrained by the toxicity to normal cells and the emergence of drug resistance in cancer cells, highlighting an urgent need for novel anticancer compounds effective against both wild-type and T790M-positive EGFR-expressing NSCLC." (PMID 40076971, 2025). "Like EGFR and RAS, MYC is a viable target for pharmacological modulation, offering promising therapeutic options for cancer treatment." (PMID 39858030, 2025). "Results included known cancer driver genes on eccDNA were identified, such as MYC, EGFR, CCND1 and MDM2." (PMID 40478912, 2025). "Based in treatment options for other cancers, we identified some potential targetable genomic alterations such as PIK3CA and EGFR to help the selection of patients with PSCC for future clinical trials with targeted therapies including Alpelisib and Cetuximab." (PMID 39222919, 2025). "This, in turn, enhances the expression of transforming growth factor-β (TGF-β), activates epidermal growth factor receptor (EGFR), and inhibits LATS1 and LATS2, leading to cancer cell proliferation." (PMID 40699764, 2025). "Specifically, molecular targeted therapeutic drugs, such as inhibitors of VEGF, EGFR, and HER2, play a pivotal role in the management of malignant tumors, with their effectiveness being closely tied to the composition of the intestinal microbiota." (PMID 39948481, 2025). "Guided by these results, we developed a highly multiplexed PRM assay for precise quantitation of 90 proteins that are associated with cancer metabolism, RNA regulation, and major cancer pathways, such as PI3K/AKT/mTOR and EGFR/RAS/RAF." (PMID 39723668, 2025).
cancer (continued). "Cellular growth factors and its kinase pathways, such as epidermal growth factor receptor (EGFR), have been used as cancer therapies for decades and are now proposed for central nervous system (CNS) neurodegenerative diseases." (PMID 40444141, 2025). "EGFR, located on the luminal side of the BBB, plays a key role in the infiltration of cancer cells and the facilitation of brain metastasis." (PMID 40806198, 2025). "Over recent decades, therapeutic strategies have evolved from traditional cytotoxic agents like platinum-based compounds and taxanes to targeted therapies that inhibit molecular drivers (e.g., EGFR, HER2, BRAF) and cancer vaccines." (PMID 40430901, 2025). "Background/Objectives: The dual targeting of epidermal growth factor receptor (EGFR) and human epidermal growth factor receptor 2 (HER2) represents an effective approach for cancer treatment." (PMID 40732338, 2025). "Apart from the more immunosuppressive microenvironment, monophasic tumors are characterized by higher expression of cancer-related genes CDKN2A, EGFR, and PDGFRL, which can be considered as potential targets for treatment." (PMID 41155410, 2025). "In summary, Hub-EGFR.Sig plays an important role in the TIME of pan-cancer, but there is heterogeneity in different types of cancer." (PMID 40574864, 2025). "To investigate the activation status of EGFR and its downstream signaling pathways, we performed a comparative analysis between PC9 and A549 cancer cell lines." (PMID 40210802, 2025). "In vitro, anti-CTLA-4 antibody activates EGFR pathway in CTLA-4 expressing cancer cells, induces cell proliferation as well as the expression of PDL-1 in the cancer cells." (PMID 40109334, 2025). "This analysis revealed upregulation of ERBB growth factor signaling to cancer cells post treatment, with increased communications received via all ERBB growth factor receptors (EGFR/ERBB1, HER2/ERBB2, HER3/ERBB3, and HER4/ERBB4)." (PMID 40341770, 2025). "The molecular docking findings also showed stable interactions with MAPK, EGFR, and Caspase9, further confirming that MGF can trigger cancer cell apoptosis by targeting cell membrane receptor factors and inhibiting cell proliferation." (PMID 40699827, 2025). "The obtained data supports the involvement of EGFR and IGF-IR in EMT-related gene regulation in cancer." (PMID 40943584, 2025). "Cancer progression is significantly influenced by aberrant signaling through receptor tyrosine kinases (RTKs), including c-MET, EGFR, VEGFR, PDGFR, HER2/HER3, and FLT3." (PMID 39924521, 2025). "Other biomarkers used in specific types of cancers include human epidermal growth factor receptor 2 (HER2) and epidermal growth factor receptor (EGFR)." (PMID 40076201, 2025). "Genetic manipulations of ERBIN expression were complemented by pharmacological manipulation of TGFBR and EGFR, leading to the conclusion that TGFBR and EGFR signaling pathways collaborate to promote EMT in breast and lung (cancer) epithelial cells." (PMID 40859866, 2025). "Our results are consistent with other studies that have developed multi-epitope vaccines targeting cancer antigens such as CEA, MUC1, and EGFR in CRC." (PMID 40599850, 2025). "The expression of MHC-I, β2M, and other APM components in cancer has been shown to be influenced by a number of oncogenic pathways, including the c-MYC, n-MYC, HER2, MAPK, and EGFR." (PMID 40098955, 2025). "FAM129B is also phosphorylated via the epidermal growth factor receptor (EGFR), which in turn activates RAS signaling, essential for the growth, survival, and invasion of cancer cells." (PMID 39941813, 2025).